ADAMTS19 (ADAM metallopeptidase with thrombospondin type 1 motif 19)
Synonyms: CVDP2
Gene: Protein-coding gene on chromosome 5 (129,459,686 to 129,738,683, forward strand). Ensembl gene ENSG00000145808.
Subcellular location: Secreted, extracellular space, extracellular matrix
Subcellular location (Human Protein Atlas): Midbody; Vesicles; Predicted to be secreted
Pathways (Reactome):
Disease: Defective B3GALTL causes PpS
Metabolism of proteins: O-glycosylation of TSR domain-containing proteins
Genetic constraint (gnomAD): Loss-of-function variants: 78 observed, 113.44 expected, observed/expected ratio (o/e) 0.69, 90% interval 0.57 to 0.83. The synonymous counts are far from expectation, so gnomAD's model fits this gene poorly and the ratio says little. Missense variants: 1,289 observed, 1,251.7 expected, observed/expected ratio (o/e) 1.03, 90% interval 0.98 to 1.08. Synonymous variants: 531 observed, 449.18 expected, observed/expected ratio (o/e) 1.18, 90% interval 1.1 to 1.27.
Gene-disease validity (ClinGen):
ClinGen rates the evidence that ADAMTS19 causes each of these diseases.
congenital heart disease (autosomal recessive): Limited. A heart disease that is present at birth.
Homologues: Orthologues: chimpanzee ADAMTS19 (99% identical), macaque ADAMTS19 (98% identical), pig ADAMTS19 (94% identical), dog ADAMTS19 (94% identical), mouse Adamts19 (87% identical), rat Adamts19 (87% identical), guinea pig ADAMTS19 (86% identical), rabbit ADAMTS19 (74% identical), tropical clawed frog adamts19 (70% identical). Paralogues in human: ADAMTS17 (50% identical), ADAMTS12 (29% identical), ADAMTS7 (29% identical), ADAMTS20 (29% identical), ADAMTS18 (28% identical), ADAMTS9 (28% identical), ADAMTS16 (28% identical), ADAMTS6 (27% identical), ADAMTS10 (25% identical), ADAMTS15 (24% identical), ADAMTS14 (24% identical), ADAMTS2 (24% identical), and 13 more.
Diseases named in the same sentence as ADAMTS19 in open-access papers:
ADAMTS19 is named in the same sentence as 33 diseases in open-access papers, as found by Europe PMC text mining. Sharing a sentence is not in itself a finding about the gene and the disease. The quoted sentences say what the papers report.
gastric cancer (4 papers, 2021 to 2025). A primary or metastatic malignant neoplasm involving the stomach. "In gastric cancer, decreased S100A16 expression is involved in miR-6884-5p and ADAMTS19 (A Disintegrin and Metalloproteinase with Thrombospondin motifs 19) inhibition of GC cells migration, invasion, and EMT, however, the role of S100A16 itself in GC metastasis has not been fully clarified yet." (PMID 34650982, 2021).
colorectal cancer (3 papers, 2015 to 2021). A primary or metastatic malignant neoplasm that affects the colon or rectum. "Survival analysis revealed that patients with low ADAMTS19 expression have worse OS than high ADAMTS19 patients, which is consistent with the findings of a study on colorectal cancer." (PMID 33921267, 2021). "Hypermethylation of the ADAMTS19 gene has been observed in gastrointestinal cancers, and epigenetic inactivation of ADAMTS19 can promote metastatic spread in colorectal cancer." (PMID 33921267, 2021). "We were intrigued by the observation that ADAMTS19 hypermethylation was the most common epigenetic alteration observed in gastric and colorectal cancers among the many loci analyzed by unbiased MS-AFLP fingerprinting." (PMID 26634009, 2015). "Similar studies have also found that ADAMTS19 is highly methylated in colorectal cancer." (PMID 32884571, 2020). "In a previous work, we found ADAMTS19 frequently hypermethylated in colorectal cancer (CRC)." (PMID 26634009, 2015). "To investigate whether ADAMTS19 hypermethylation was exclusive of gastric and colorectal cancers, we analyzed 356 primary tumor samples from other malignancies." (PMID 26634009, 2015). "Moreover, ADAMTS19 is downregulated and correlates with prognosis in colorectal cancer." (PMID 33921267, 2021).
breast carcinoma (2 papers, 2015 to 2022). "ARFGEF2:SULF2 fusion was also called for MCF-7 cell line and SLC27A6:ADAMTS19 was previously identified in breast cancer with short reads." (PMID 35164688, 2022).
nanophthalmos (2 papers, 2021). "Three of the candidate genes discovered in our GWAS for eye size – PRSS56, ADAMTS19, and PIEZO2 – are of particular interest by virtue of their known or suggested role in causing nanophthalmos or microphthalmos." (PMID 34698770, 2021). "Using two distinct mouse models of nanophthalmos and a combination of genetic approaches, we identified a retinal gene expression signature characterized by the upregulation of the genes coding for PRSS56 and ADAMTS19 that is associated with the reduced ocular size." (PMID 33755662, 2021).
ovarian carcinoma (2 papers, 2015 to 2025). A malignant neoplasm originating from the surface ovarian epithelium. "The clustering of KRAS and ADAMTS19, genes known to be involved in endometriosis-associated ovarian cancer, also provides a molecular foundation for potential malignant transformation, emphasizing the disease’s multifaceted impact." (PMID 41516028, 2025). "None of the serous or endometrioid type tumors, which are the most frequent types of ovarian cancer, exhibited ADAMTS19 hypermethylation." (PMID 26634009, 2015). "Moreover, the gene KRAS, known to be mutated in endometriosis-associated ovarian cancer (EAOC), shows clustering with the gene ADAMTS19, which is known to promote proliferation and invasion in EAOC cells." (PMID 41516028, 2025).
premature ovarian failure (2 papers, 2015 to 2023). "Polymorphisms in human ADAMTS19 are associated with premature ovarian failure." (PMID 37656189, 2023). "We focused first on the ovarian gene Adamts19 (a disintegrin-like and metallopeptidase [reprolysin type] with thrombospondin type 1 motif, 19), identified in a PCR-based cDNA subtraction screen, and in which polymorphisms have since been associated with premature ovarian failure (POF;." (PMID 25629157, 2015).
adenoma (1 paper, 2015). A neoplasm arising from the epithelium. "ADAMTS19 hypermethylation was frequent in adenomas and showed a trend for decreasing frequency during tumor progression." (PMID 26634009, 2015). "ADAMTS19 hypermethylation frequency was higher in adenomas (47.6 %) than in carcinomas (34.6 %) or metastases (30.9 %)." (PMID 26634009, 2015). "This suggests that ADAMTS19 hypermethylation could be detrimental for tumor progression, i.e., adenomas with ADAMTS19 hypermethylation would be less likely to become malignant or carcinomas less metastatic." (PMID 26634009, 2015). "ADAMTS19 was hypermethylated in 48 % of adenomas, 35 % of adenocarcinomas, and 31 % of metastases but never in the 322 normal tissues corresponding to the tumoral samples." (PMID 26634009, 2015).
aortic stenosis (1 paper, 2020). Aortic valve stenosis is a aortic valve disease caused by the incomplete opening of the aortic valve. "Of the homozygous Adamts19 knockout mice, 38% showed aortic valve regurgitation and/or aortic stenosis at three months of age, confirming an important role of ADAMTS-19 in aortic valve physiology." (PMID 33352066, 2020).
aortic valve disease (1 paper, 2023). "Whole exome sequencing in two unrelated families with consanguineous parents identified four individuals with early onset aortic valve disease that carried two rare homozygous loss-of-function mutations in ADAMTS19." (PMID 37569511, 2023). "Additionally, although ADAMTS19 proteoglycanase activity has not been characterized in vitro, an involvement in PG regulation has been proposed based on the phenotype of Adamts19 knockout mice as well as the clinical presentation of patients with aortic valve disease." (PMID 37569511, 2023).
aortic valve insufficiency (1 paper, 2023). Dysfunction of the aortic valve characterized by incomplete valve closure. "Moreover, ADAMTS19 variants were found to cause a spectrum of congenital heart valve diseases, including AVS, aortic valve insufficiency, subaortic stenosis, pulmonary valve stenosis, pulmonary valve insufficiency and atrioventricular valve insufficiency." (PMID 37187784, 2023).
asthma (1 paper, 2020). "Several genes intersect in asthma phases, in which RAB24 and ADAMTS19 are located in the same branch in a set of moderate-to-severe asthma genes; these genes are linked to immune gene airway diseases and autophagy, suggesting the involvement of these genes in the pathogenesis of asthma." (PMID 32512817, 2020).
dementia (1 paper, 2025). Loss of intellectual abilities interfering with an individual's social and occupational functions. "We identified a SNP in ADAM metallopeptidase with thrombospondin type 1 motif 19 (ADAMTS19) that was associated with dementia in individuals with onset less than 75 years (rs67540991, p = 2.27 × 10–7)." (PMID 40708016, 2025).
gynecological cancers (1 paper, 2015). "Tumor-specific methylation of ADAMTS19 was significantly more frequent in gastrointestinal than in gynecological cancers (odds ratio (OR) = 2.9, confidence interval (CI) = (1.9–4.7), p = 5.2 × 10−7) and was independent of the methylation of adjacent loci in CRC." (PMID 26634009, 2015).
heart valve disorder (1 paper, 2020). A disease involving the cardial valve. "The authors suggested that a unique feature results from these ADAMTS19 mutations, causing only heart valve disorders without affecting any other organs; this indicates non-syndromic features." (PMID 32183147, 2020).
lymph node metastasis (1 paper, 2021). "Univariate analysis identified five prognostic indicators: invasion depth, lymph node metastasis, distant metastasis, vessel invasion, and ADAMTS19 expression." (PMID 33921267, 2021).
mucinous ovarian cancer (1 paper, 2015). An invasive malignant neoplasm that arises from the ovary and is characterized by the presence of malignant epithelial cells that contain intracytoplasmic mucin and may resemble the epithelial cells of the endocervix or gastrointestinal tract. "Our results highlight the frequent involvement of ADAMTS19 epigenetic silencing in CRC and mucinous ovarian cancer." (PMID 26634009, 2015).
ovarian clear cell cancer (1 paper, 2024). An invasive malignant neoplasm that arises from the ovary and is characterized by a predominance of clear and hobnail malignant epithelial cells. "We examined the mRNA and protein expression of ADAMTS19 and TUBB in normal ovarian epithelial IOSE80 cell and ovarian clear cell carcinoma ES-2 cell and ovarian endometrioid carcinoma TOV-112D cell by RT-qPCR and immunohistochemical staining." (PMID 39113897, 2024).
pancreatic cancers (1 paper, 2015). "In the TCGA datasets ADAMTS19 was frequently hypermethylated in gastrointestinal cancers including stomach (47.6–53.7 %), esophageal (39.8 %), liver (30.9 %), colorectal (22.2–25.2 %), and pancreatic cancers (13.8 %)." (PMID 26634009, 2015).
tumor (5 papers, 2012 to 2025). "We further performed mechanistic experiments and rescue assays and demonstrated that S100A16 is the downstream of ADAMTS19, acting as a tumor promoter involved in carcinogenesis." (PMID 33921267, 2021). "The results confirmed that hypermethylation of ADAMTS19 was exclusive of the tumor tissues and extended throughout the gene promoter region." (PMID 26634009, 2015). "In support of this hypothesis, some of the clones from ADAMTS19 methylation-positive tumor samples analyzed by bisulfite sequencing were essentially unmethylated, resembling the methylation pattern of the normal tissue." (PMID 26634009, 2015). "Our in vitro studies indicate that ADAMTS19 downregulation reduces the motility of cancer cells, suggesting that ADAMTS19 hypermethylated cells could be less capable to escape the tumor mass and migrate to distant organs through the vascular system." (PMID 26634009, 2015). "Similarly, a high level of metalloprotease ADAMTS19 expression was observed in several tumor tissues and cell lines." (PMID 22532847, 2012). "Hence, we speculate that ADAMTS19 is a tumor inhibitor and plays a crucial role in the pathogenesis of GC." (PMID 33921267, 2021). "Our published results with the B16F1 model already determined a clear impairment of tumour progression in the absence of stromal ADAMTS19." (PMID 30166561, 2018). "Therefore, it is possible that in vivo ADAMTS19 hypermethylation exerts a stronger negative effect on the migration capabilities of tumor cells." (PMID 26634009, 2015). "ADAMTS19 methylation in primary CRC did not associate with gender, race, age, or tumor location." (PMID 26634009, 2015).
cancer (4 papers, 2012 to 2022). A tumor composed of atypical neoplastic, often pleomorphic cells that invade other tissues. "The Oncomine analysis revealed that ADAMTS19 mRNA levels were significantly lower in cancer tissues than in adjacent normal tissues (median rank: 1450.5, p < 0.001)." (PMID 33921267, 2021). "Nothing is essentially known about the function of ADAMTS19 or its possible role in cancer." (PMID 26634009, 2015). "Noteworthy, several candidate susceptibility genes (PRKCA, BMP6, ADAMTS19, ARHGAP6, FUT9/8, FAM108C1, CHL1, BTBD9 and WDR52) are involved in the actin cytoskeleton arrangement, cell adhesion and cell motility processes, which are important for cancer invasion and metastasis." (PMID 22532847, 2012). "In this report, we characterized the promoter region of ADAMTS19 frequently hypermethylated in CRC and extended this observation to other cancers." (PMID 26634009, 2015). "Using qRT-PCR and IHC, we found that ADAMTS19 is downregulated in cancer tissues compared to adjacent normal tissues." (PMID 33921267, 2021).
cardiac diseases (1 paper, 2020). "It is noteworthy that two recently discovered Mendelian disorders arising from ADAMTS9 and ADAMTS19 broadened the spectrum of affected organs (renal and cardiac diseases, respectively) that have never been associated with six previously identified ADAMTS genes responsible for Mendelian disorders." (PMID 32183147, 2020).
infection (1 paper, 2022). The state of being infected such as from the introduction of a foreign agent such as serum, vaccine, antigenic substance or organism. "A number of non-infection associated genes that encode secreted proteins with potential to influence the phenotype of the infected cell and/or cells of the host immune system were also identified (e.g. IL9, CXCL2, CLEC3B and ADAMTS19)." (PMID 35061738, 2022).
neurological disorders (1 paper, 2021). "In cell-conditioned medium of cortical neurons, KLK6 activated matrix metalloproteinase 2 (MMP2) and a disintegrin and metalloproteinase with thrombospondin motif 19 (ADAMTS19), all members of the proteolytic and regulatory network in neurological disorders, triggering α-synuclein processing." (PMID 34439122, 2021).
ADAMTS19 also shares sentences with these, for which no sentence is quoted: adenocarcinoma (1 paper); Bicuspid aortic valve (1); cardiac valvular dysplasia 2 (1); clear cell renal carcinoma (1); endometriosis (1); hyperopia (1); Mendelian diseases (1); myopia (1); ovarian endometrioid carcinoma (1); pulmonary valve stenosis (1).